IGF1 (insulin like growth factor 1)
Diseases named in the same sentence as IGF1 in open-access papers (continued):
Sharing a sentence is not in itself a finding about the gene and the disease.
asthma (continued). "In addition, pre-clinical studies using mouse models of asthma showed that IGF-1 is upregulated in lung tissue, and the administration of IGF-1-neutralizing antibodies reduced airway resistance and inflammation." (PMID 36160852, 2022). "Besides its induction during asthma, IGF1 is also induced in lung of mice exposed to high doses of aerosolised LPS." (PMID 30182191, 2018). "In contrast, IGF-1 is among the proinflammatory mediators upregulated by creatine supplementation that exacerbates goblet cell proliferation and IL-5 and iNOS expression by epithelial cells in an asthma model." (PMID 30018981, 2018). "Thus data are insufficient for reaching the conclusions that congenital or prenatal IGF-1 signaling abnormality contributes to the development of asthma." (PMID 30018981, 2018). "A recent study discloses novel roles of IGF-1/IGF-1R signaling in asthma." (PMID 30018981, 2018). "From these data we can conclude that both Igf1r and Igf1 may be important mediators in the establishment of murine asthma, and that Igfpb3 and Igfpb5 could play protective roles against HDM-induced allergic inflammation." (PMID 29272313, 2017). "Indeed, IGF-1 may play a crucial role in asthma, especially in airway hyperresponsiveness, airway inflammation, as well as smooth airway hyperplasia." (PMID 36936149, 2023). "The apparently contradictory results regarding IGF-1 and asthma can be explained in part by the fact that preclinical models measured IGF-1 in the lungs, while epidemiological studies assessed circulating serum IGF-1 levels, which may have disparate impacts on and airway inflammation." (PMID 36936149, 2023). "Using the well-accepted ovalbumin (OVA)-induced model of asthma, the laboratory examined the impact of CR supplementation on the characteristic airway inflammation and remodeling in mice that is induced by the strong Th2 response dominated by IL-4, IL-5, and insulin-like growth factor-1 (IGF-1)." (PMID 33652752, 2021). "IGFBP-3 suppresses VEGF production by both IGF-1-dependent and hypoxia-inducible factor- (HIF-) dependent mechanisms, while VEGF has been shown to be associated with subepithelial fibrosis by regulation of TGF-β1 expression through the PI3K/AKT signaling pathway in asthma." (PMID 30018981, 2018). "There are several evidences suggesting that IGF1 may also contribute to asthma." (PMID 22235296, 2012). "The different growth factors involved in the pathophysiology of asthma include PAF, transforming growth factor (TGF-β), nerve growth factor (NGF), fibroblast growth factor (FGF), epidermal growth factor (EGF), and insulin-like growth factor 1 (IGF-1)." (PMID 37233255, 2023). "The most influential nodes (Fn1, Igf1, Ccl2, C3, Timp1, Cxcl12, Ccl4, Ccr2, Spp1, C3ar1, Cat, Cyp2e1, Muc5ac, Muc5b) were selected for further validation in the OVA-induced asthma and post-asthmatic fibrosis murine model." (PMID 35625754, 2022). "In mice, IGF1 mediates allergic airway inflammation, and IGFBP3 was shown to block the effects of asthma." (PMID 34440118, 2021). "IGFBP-3 inactivates NF-κB signaling pathway in asthma in that it degrades IκBa and p65-NF-κB through IGFBP-3 receptor-mediated, IGF-1-independent activation of caspases, which further blocks TNF-α-induced inflammation and eosinophil migration." (PMID 30018981, 2018). "Being as the basis for asthma treatment, steroids appear to inactivate IGF-1/IGF-1R signaling indirectly or directly by downregulating the expression of IGF-1 and IGF-1R both locally and systemically." (PMID 30018981, 2018). "As has been reviewed, IGF-1 signaling pathway and IGFBP-3 are of therapeutic significance in asthma." (PMID 30018981, 2018). "PPP3CB (also known as calcineurin) and IGF1 identified by SSH share common signaling pathways also possibly contributing to smooth muscle phenotype switching and ECM remodeling in asthma." (PMID 22235296, 2012). "Our findings showed consistency with several but not all previous studies of the role of IGF-1 in asthma." (PMID 36936149, 2023).
asthma (continued). "Both in asthma and COPD abnormal IGF-1 signaling has been demonstrated." (PMID 32509795, 2020). "IGF-1 increases mRNA and protein expression of the IL-4-induced type II IgE receptor (FcεRII/CD23) in B cells, suggesting its immunomodulatory potential in asthma." (PMID 30018981, 2018). "HDM-mediated induction of Igf1 could be responsible for IGF1R phosphorylation to promote the asthmatic response, and therefore supports why targeting IGF1R with NVP ameliorates HDM-induced asthma." (PMID 34440118, 2021). "Migration of airway epithelial cells could be stimulated by IL-4, possibly via IRS-1/IRS-2 signaling independent of IGF-1/IGF-1R in an asthma model." (PMID 30018981, 2018). "Another putative mediator of severe asthma, IL-17F, has been shown to induce IGF-1 expression in bronchial epithelial cells along or by costimulation with IL-4 and IL-13, suggesting an important relationship among IGF-1 signaling, Th2, and Th17 cells in asthma." (PMID 30018981, 2018). "A negative correlation was found between GH, IGF-1, and IGFBP3 levels and asthma severity (p < 0.05)." (PMID 38754227, 2024).
COVID-19 (41 papers, 2021 to 2025). A disease caused by infection with severe acute respiratory syndrome coronavirus 2. "Meanwhile, in a study comparing critically and non-critically ill patients, low insulin growth-like factor-1 (IGF-1) levels showed a potential association with severe forms of COVID-19." (PMID 36836216, 2023). "In the reverse direction, we found that very severe respiratory syndrome was associated with IGF-1 levels, and COVID-19 susceptibility was associated with testosterone levels." (PMID 36836216, 2023). "It has been shown that higher serum IGF-1 concentrations are associated with a lower COVID-19 severity." (PMID 37189123, 2023). "The MR-PRESSO global test suggested potential horizontal pleiotropy effects associated with very severe respiratory syndrome COVID-19 and susceptibility to IGF-1 and the three COVID-19 phenotypes with testosterone (all p-values < 0.05)." (PMID 36836216, 2023). "We found suggestive evidence for associations between genetic liability to high IGF-1 levels and decreased risk of COVID-19 susceptibility and hospitalization." (PMID 36250974, 2022). "In conclusion, our study indicated that genetically predicted high IGF-1 levels were associated with decrease the risk of COVID-19 susceptibility and hospitalization, but these associations did not survive the Bonferroni correction of multiple testing." (PMID 36250974, 2022). "Higher genetically predicted IGF-1 levels have nominally significant association with reduced risk of COVID-19 susceptibility and hospitalization." (PMID 36250974, 2022). "Our findings suggest a potential role of IGF-1 in COVID-19 risk and have implications for tailored treatment of COVID-19 patients." (PMID 36250974, 2022). "There is one observational study that demonstrated an inverse association between pre-diagnostic circulating levels of IGF-1 and COVID-19 mortality risk among COVID-19 patients in UK Biobank." (PMID 36250974, 2022). "Our study indicated that genetically predicted high IGF-1 levels were associated with decrease the risk of COVID-19 susceptibility and hospitalization, but these associations did not survive the Bonferroni correction of multiple testing." (PMID 36250974, 2022). "Reduced circulating levels of IGF1 or IGFALS were found to be associated with COVID-19 mortality or in severe COVID-19 patients with adverse prognosis in two separate studies." (PMID 35958562, 2022). "In sum, downregulation of serum levels of inflammatory cytokines and IGF1 is associated with the recovery of COVID-19 patients." (PMID 35095832, 2021). "Furthermore, individuals with low serum IGF1 levels are at a higher risk of developing COVID-19 compared to those with normal serum levels." (PMID 40371107, 2025). "Higher IGF1 levels were associated with better survival of patients with severe COVID-19." (PMID 38255230, 2024). "Previous studies have associated IGFBP-2, IGF1 with adverse outcomes in COVID-19 patients." (PMID 39802657, 2024). "In addition to testosterone levels, we also observed that COVID-19 severity was associated with increased levels of IGF-1." (PMID 36836216, 2023). "We assessed the causal association of three COVID-19 phenotypes with insulin-like growth factor 1, estrogen, testosterone, dehydroepiandrosterone (DHEA), thyroid-stimulating hormone, thyrotropin-releasing hormone, luteinizing hormone (LH), and follicle-stimulating hormone." (PMID 36836216, 2023). "However, the MR-PRESSO global test suggested horizontal pleiotropy in the association of IGF-1 and testosterone with COVID-19 phenotypes (p-value < 0.05)." (PMID 36836216, 2023). "The test confirmed that higher values of indices estimating the amount of scarring and steatosis in the liver, as well as low levels of liver attenuation, IGF-1, and zSDS–IGF-1 values, are associated with the need for ventilation or occurrence of death in COVID-19 patients." (PMID 36851702, 2023).
COVID-19 (continued). "For the analysis using COVID-19 as exposure, heterogeneity was found in the association among very severe respiratory syndrome, susceptibility, and IGF-1 and in the association between very severe respiratory syndrome and testosterone (p < 0.001 for all analyses)." (PMID 36836216, 2023). "However, a phenome-wide association study found that genetically determined severe COVID-19 was associated with lower IGF-1 levels." (PMID 36836216, 2023). "Finally, we constructed a risk signature in three genes (MET, UCHL1, IGF1) correlated to COVID-19 in IPF by conducting Lasso Cox Regression analyses." (PMID 36147332, 2022). "Our MR analyses found a negative association between genetically determined high circulating IGF-1 levels and decreased risk of COVID-19 susceptibility and hospitalization, indicating IGF-1 may be a protective factor of COVID-19 risk." (PMID 36250974, 2022). "Further studies are needed to validate the findings and explore whether IGF-1 could be a potential intervention target to reduce COVID-19 risk." (PMID 36250974, 2022). "It should also be noted that the study findings are based on evidence from genetic data, additional large and prospective cohort studies with available IGF-1 data and information on COVID-19 susceptibility and clinical outcomes are needed to validate the findings." (PMID 36250974, 2022). "Insulin-like growth factor (IGF-1) was previously found associated with COVID-19 mortality in UKBB." (PMID 35222515, 2021). "Moreover, a recent study indicated that low serum IGF-1 levels were associated with a higher risk of mortality in COVID-19 patients." (PMID 34667241, 2021). "Furthermore, UKBB patients in the highest quartile of IGF-1 had a 41% lower risk for COVID-19 mortality than patients in the lowest quartile." (PMID 35222515, 2021). "This is an observational study that evaluated associations of sex hormones and IGF-1 with COVID-19." (PMID 34032853, 2021). "The identification of altered biomarkers such as osteocalcin, PINP, ALP, OPN, COMP, HA, IGF-1, myostatin, follistatin, and creatine kinase can provide a foundation for developing minimally invasive diagnostic tools to detect early bone, cartilage, and muscle involvement in COVID-19 patients." (PMID 40943488, 2025). "In addition, studying the immune responses underlying the different clinical presentations of COVID-19 in relation to the GH/IGF-1 axis could unveil new targets for more effective treatments." (PMID 36851702, 2023). "It suggests that we need to better understand the effects of GH/IGF-1 on RAAS under physiological and pathological conditions and the cascade of effects, which will help us understand the role of GH/IGF-1 in COVID-19." (PMID 40860776, 2025). "Several COVID-19 studies report alterations in IGF-1 during infection with implications for muscle wasting." (PMID 40943488, 2025). "Six patients in the CAM2029 arm and 1 patient in the placebo arm had protocol deviations whereby >35 days elapsed between the last treatment dose and the final sample being taken for IGF-1 measurement; 3 of these were due to COVID-19-related disruptions." (PMID 39378125, 2025). "After six months of infection, patients who developed severe COVID-19 presented reduced GH and IGF-1, as compared with controls, whereas the insulin levels were not different." (PMID 40709999, 2025). "IGF1 was found to be low in the serum of patients with severe COVID-19, and the present analysis showed that this is in parallel with a rise in serum IGFBP-2 levels." (PMID 38255230, 2024). "Serum IGF1 levels were found to be reduced in severe COVID-19 patients, in contrast to patients with mild disease." (PMID 38255230, 2024). "Survivors of severe COVID-19 often exhibit higher IGF-1 levels, while those with lower IGF-1 tend to have worse outcomes." (PMID 39585162, 2024). "In the univariate analysis with COVID-19 severity as an outcome, heterogeneity was found in IGF-1 and testosterone estimates." (PMID 36836216, 2023).
COVID-19 (continued). "This retrospective study evaluated the GH/IGF-1 axis status at the time of hospital admission in a cohort of patients hospitalized for COVID-19." (PMID 36851702, 2023). "The calculated cut-off values of serum IGF-1 and H-FABP represent a promising non-invasive prognostic tool that would facilitate the risk stratification in COVID-19 patients, and control the morbidity/mortality associated with progressive infection." (PMID 37189123, 2023). "We found that IGF-1 can be a simple and accurate tool to predict mortality or the need for ventilation in patients with COVID-19, as seen by other authors." (PMID 36851702, 2023). "The study aimed to investigate the association of concentrations of serum testosterone, estradiol, and insulinlike growth factor 1 (IGF-1, concentrations of which are regulated by sex hormone signaling) with COVID-19 severity." (PMID 36303865, 2022). "MMP-7, TGF-β, CCL2, CCL-3, CXCL-10, G-CSF, IFN gamma, IL-10, IL-2, IL-4, IL-6, IL-7, TNF-α, IL-6, and IGF-1 were studied for their correlation to lung involvement in COVID-19 patients." (PMID 36286038, 2022). "Testosterone, SHBG, IGF-1, and COVID-19 outcomes in Mendelian randomization (MR) analyses adjusting BMI." (PMID 36250974, 2022). "Another observational study in Greece reported lower IGF-1 levels in critically ill COVID-19 patients compared to their counterparts with less severe disease or without COVID-19." (PMID 36250974, 2022). "MMP-7, TGF-β, CCL2, CCL-3, CXCL-10, G-CSF, IFN gamma, IL-10, IL-2, IL-4, IL-6, IL-7, TNF-α, IL-6, and IGF-1 were studied for their correlation with mortality in all 40 COVID-19 patients." (PMID 36286038, 2022). "This study aimed to examine associations of sex hormone, sex hormones-binding globulin (SHBG), insulin-like growth factor-1 (IGF-1), and COVID-19 risk." (PMID 36250974, 2022). "The authors found each 1-standard deviation increase in log-transformed IGF-1 reduced odds of COVID-19 mortality by 15% (OR = 0.85, 95% CI: 0.73–0.99)." (PMID 35222515, 2021). "Further investigation of pQTLs in PDE3A and IGF-1 will be needed to confirm the genetic relationship between these two proteins and COVID-19." (PMID 35222515, 2021). "Similarly, muscle-related biomarkers, including IGF-1, myostatin, follistatin, and creatine kinase further highlight the profound impact of COVID-19 on skeletal muscle mass, function, and recovery potential." (PMID 40943488, 2025). "In patients with COVID-19, the IGF1 levels are elevated during the early stages of infection." (PMID 40371107, 2025). "However, it has also been reported that patients with severe COVID-19 and healthy controls have comparable serum levels of IGF1." (PMID 38255230, 2024). "At all timepoints, GSEA suggested a pronounced activation of neutrophils, platelets and coagulation in COVID-19, but also enrichment of the Wound healing GO term (including genes IGF1 and SDC1), suggesting ongoing immune activation by Danger-Associated Molecular Patterns (DAMPs)." (PMID 37365222, 2023). "To confirm our hypothesis, we conducted a retrospective analysis of the GH/IGF-1 axis in COVID-19 patients and evaluated several baseline factors to see which were associated with worse outcomes." (PMID 36851702, 2023). "In conclusion, our results may shed light on the possible role of IGF-1 as a new metabolic health parameter capable of effectively predicting the development of more severe forms of COVID-19." (PMID 36851702, 2023). "Additional studies are warranted to further explore the potential therapeutic appropriateness of GH replacement therapy targeting the IGF-1 pathway in specific subgroups of COVID-19 patients with low IGF-1 levels who, as shown here, are at high risk of developing more severe disease." (PMID 36851702, 2023). "Taken together, these studies provide biological evidence supporting that IGF-1 might be an important anti-inflammatory factor in the alveolar microenvironment and thus may contribute to improve COVID-19 outcomes." (PMID 36250974, 2022).